MTOR (mechanistic target of rapamycin kinase)
Diseases named in the same sentence as MTOR in open-access papers (continued):
Sharing a sentence is not in itself a finding about the gene and the disease.
Hyperinsulinemia (continued). "This indicates that HED, which resulted in hyperinsulinemia and increased activation of p-mTOR, could also trigger senescence in cancer cells harbored by the host." (PMID 25895126, 2015). "While metabolic pathways remain blocked, hyperinsulinemia selectively activates renal growth pathways, promoting cellular hypertrophy and fibrosis via redox-sensitive kinases (ERK, JNK, mTOR/S6K1)." (PMID 41601879, 2026). "Mechanistically, both conditions converge on shared pathways such as chronic inflammation, hyperinsulinemia, immune suppression, and activation of pro-metastatic signaling cascades including PI3K/Akt/mTOR." (PMID 41139205, 2025). "T2DM promotes colorectal tumor growth through mechanisms such as hyperinsulinemia, which activates the pro-growth PI3K/AKT/mTOR signaling pathway in colonic epithelial cells." (PMID 41374004, 2025). "Hyperinsulinemia activates critical signaling pathways, such as PI3K/AKT, mTOR, and Ras/MAPK, which drive cell proliferation, survival, and resistance to apoptosis." (PMID 39290325, 2024). "IR leads to an increase in hyperinsulinemia, which in turn triggers the activation of phosphoinositide 3-kinase/protein kinase B/mammalian target of rapamycin, known as the PI3K/Akt/mTOR signaling pathway in CRC." (PMID 38541854, 2024). "Hyperinsulinemia increases the biological activity of IGF-1, which induces and activates the Ras/Raf/MAPK and PI3K/Akt/mTOR pathways, thus reduces apoptosis promotes cell proliferation and survival, and increases the risk of tumor development." (PMID 37736725, 2023). "In addition, increased growth factor signaling, as suggested by increased phosphorylation of Akt1, and expression of extracellular-signal regulated kinases (ERK) 1/2 and the mechanistic target of rapamycin (mTOR) was observed, which could be related to hyperinsulinemia in these offspring." (PMID 28684678, 2017). "Maternal hyperinsulinemia can also stimulate placental glucose uptake and SNAT, and the placenta appears to not develop insulin resistance, resulting in overactivation of amino acid uptake via mTOR signaling." (PMID 37512552, 2023). "Hyperinsulinemia resulted in increased phosphorylation of Akt and mTOR with reduced nonphosphorylation of 4E‐BP1 and LC3B‐II, all p < 0.0005, but this effect of insulin was not altered by administration of BHB." (PMID 35986508, 2022). "Additionally, compensatory hyperinsulinemia may activate the insulin/IGF axis, stimulating cancer-promoting signaling pathways such as PI3K/Akt/mTOR." (PMID 40597094, 2025). "However, in individuals with hyperinsulinemia, the excessive activation of insulin signaling pathways, including the phosphatidylinositol 3-kinase/protein kinase B (PI3K/AKT), mTOR, and Ras/mitogen-activated protein kinase (MAPK) pathways, significantly enhances tumor growth." (PMID 39290325, 2024). "Moreover, an increase in the phosphorylation of mTOR (Ser2448) and P70S6 kinase (Thr389) may be a consequence of hyperinsulinemia, which exacerbates the phosphorylation state." (PMID 34830360, 2021). "In addition, in high-fat-diet-fed mice both mTOR overactivation and elevated SESN2 expression were evident; we proposed that that hyperinsulinemia-evoked mTOR activation might upregulate SESN2 protein level." (PMID 25792980, 2015). "Moreover, elevated insulin levels resulting from hyperinsulinemia trigger insulin-like growth factor (IGF) signaling, activating key pathways such as phosphoinositide 3-kinase (PI3K)/protein kinase B (Akt)/mammalian target of rapamycin (mTOR) and mitogen-activated protein kinase (MAPK)." (PMID 38801466, 2024). "Furthermore, another concept to be highlighted is that hyperinsulinemia, present in insulin-resistant conditions, may favor IR-A/IGF-2 loop activation, thereby potentiating IR-A-dependent mitogenic functions via MAPK/PI3-K/mTOR signaling activation, and worsening the prognosis of TC." (PMID 30513575, 2018).
head and neck squamous cell carcinoma (83 papers, 2009 to 2026). A squamous cell carcinoma that arises from any of the following anatomic sites: lip and oral cavity, nasal cavity, paranasal sinuses, pharynx, larynx, and salivary glands. "Our results revealed, for example, the potential involvement of the mTOR pathway in the development of tumors with loss-of-function mutations of MLL2 in head and neck squamous cell carcinomas." (PMID 27095575, 2016). "Aberrations in the PI3K/AKT/mTOR pathway in head and neck squamous cell carcinoma (HNSCC) were associated with malignant characteristics." (PMID 33259779, 2021). "Accordingly, the accumulation of phosphorylated form of the RPS6, a typical downstream product of the mTOR pathway is one of the most frequent events in head and neck squamous cell carcinoma (HNSCC) especially in OSCC." (PMID 38370876, 2024). "PD‐L1 has been identified as promoting the growth of head and neck squamous cell carcinoma cells through mTOR signaling." (PMID 38355515, 2024). "Adenosine has been shown to promote apoptosis in head and neck squamous cell carcinoma through the PI3K/Akt/mTOR signaling pathway." (PMID 36072973, 2022). "In Cal-27 (a head and neck squamous cell carcinoma), xenograft mice, it has been described the activation of the Akt mammalian target of rapamycin (mTOR) signaling pathway." (PMID 34209857, 2021). "EGFR is a receptor tyrosine kinase upstream of the PI3K–Akt–mTOR pathway in head and neck squamous cell carcinomas." (PMID 34067437, 2021). "It was reported that miR-206 is involved in the progression of human head and neck squamous cell carcinoma by mediating HDAC6 through PTEN/AKT/mTOR pathway." (PMID 32833118, 2021). "The research on the pathogenesis of mTOR in squamous cell carcinoma mainly focuses on the head-neck squamous cell carcinoma, but less on CSCC." (PMID 34874800, 2021). "Meanwhile, it was revealed that in head and neck squamous cell carcinoma, inhibition of mTOR/Akt pathway signalling inhibits HDAC6." (PMID 33547375, 2021). "It is intriguing to note that PI3K/AKT/mTOR pathways would contribute to cancer cell proliferation in head and neck squamous cell carcinoma (HNSCC), possibly serving a pro-tumorigenic function." (PMID 33653351, 2021). "The cancer genome atlas (TCGA) study has revealed that a greater number of the head and neck squamous cell carcinoma (HNSCC) cases have shown an alteration in the protein kinase B (AKT)/ mammalian target of rapamycin (mTOR) pathway." (PMID 32384682, 2020). "A recent report stated that activation of epidermal growth factor receptor (EGFR)/Akt/mTOR axis acts as a positive feedback for constitutive upregulation of NF-κB subunit p65 in head and neck squamous cell carcinoma." (PMID 29381751, 2018). "Autophagy induction by inhibition of mTOR signaling can result in anti-cancer drug-resistance in head and neck squamous cell carcinoma cells." (PMID 30619741, 2018). "The PI3K/AKT/mTOR signaling pathway has emerged as one of the most frequently deregulated in head and neck squamous cell carcinomas (HNSCC)." (PMID 27119232, 2016). "mTOR inhibition has emerged as a promising strategy for head and neck squamous cell carcinomas (HNSCC) treatment." (PMID 26882569, 2016). "m6A RNA methylation may be involved in the regulation of the immune microenvironment in head and neck squamous cell carcinoma (HNSCC) in synergy with the PI3K/AKT/mTOR signaling pathway." (PMID 34956201, 2021). "Anti-proliferative effect of Orm is reported to inhibit colony forming efficiency of head and neck squamous cell carcinoma (HNSCC) cells by modulating PI3K/mTOR pathway." (PMID 38966180, 2024).
head and neck squamous cell carcinoma (continued). "Additionally, PIK3CA and/or EGFR amplification and Rictor overexpression in head and neck squamous cell carcinoma and lung squamous cell carcinoma, and the RICTOR amplification detected in our study are associated with the fact that mTOR inhibitors are under investigation in these tumours." (PMID 37949943, 2023). "The aberrant activation of the PI3K/mTOR signaling circuitry is one of the most frequently dysregulated signaling events in head and neck squamous cell carcinoma (HNSCC)." (PMID 34255745, 2021). "METTL1 knockout markedly reduced the proliferation, migration, and invasive ability of head and neck squamous cell carcinoma cells, and by decreasing the level of m7G tRNA modification inhibited oncogenic gene translation and PI3K/AKT/mTOR signaling pathway." (PMID 39289775, 2024). "Patients with head and neck squamous cell carcinoma (HNSCC) have a high risk of metastasis and recurrence, and aberrant activation of PI3K/AKT/mTOR signaling occurs in approximately 80% of HNSCC, which has been suggested as a prognostic biomarker for patients with recurrence or metastasis." (PMID 37601696, 2023). "In head and neck squamous cell carcinoma, WZ37, a curcumin analog, induced G2/M arrest and apoptosis via the oxidant-sensitive Akt/mTOR pathway." (PMID 34769290, 2021). "In head and neck squamous cell carcinoma (HNSCC), MAPK/ERK kinase (MEK)/ERK/activator protein 1 (AP-1), NF-κB and mTOR signaling pathways are frequently activated." (PMID 32175074, 2020). "In head and neck squamous cell carcinoma cell lines, inhibition of the LAT-1 transporter using an inhibitor lowered the levels of phosphorylation of mTOR and its downstream signaling molecules." (PMID 30871192, 2019). "Liu et al47 showed that miR‐206 suppressed head and neck squamous cell carcinoma cell growth, invasion and migration through targeting HDAC6 via mTOR/PTEN/AKT pathway." (PMID 30156374, 2018). "Chen at al. obtained similar results and observed down-regulation of both mTOR and IGF1R after transfection with miR-99 family members in head and neck squamous cell carcinoma." (PMID 22920721, 2012). "Moreover, neddylation of tuberous sclerosis complex 2 (TSC2) inactivates the mTOR pathway, enhancing migration, invasion, and EMT in head and neck squamous cell carcinoma (HNSCC)." (PMID 41540013, 2026). "Head and neck squamous cell carcinoma (HNSCC) exhibits limited response to EGFR blockade with cetuximab, largely due to constant activation of the PI3K/AKT/mTOR pathways." (PMID 42183362, 2026). "In addition, the upregulation of the METTL1/WDR4 complex and m7G levels in tRNA were also shown to promote the development and malignancy of head and neck squamous cell carcinoma (HNSCC) by regulating a subset of oncogenic transcripts, including genes related to the PI3K/AKT/mTOR signalling pathway." (PMID 39723662, 2025). "PI3K/mTOR inhibition leads to apoptosis of NOTCH1-mutant head and neck squamous cell carcinoma (HNSCC) cells." (PMID 36124629, 2022). "Another study discovered significant differences in the expression of EGFR/PI3K/Akt/mTOR signaling-related proteins and clinical prognosis in patients with HPV16-positive or HPV16-negative head and neck squamous cell carcinoma (HNSCC)." (PMID 36249021, 2022). "mTor activation has been observed in HPV-related cervical squamous cell carcinomas, such as cervical carcinoma, head and neck squamous cell carcinoma (HNSCC) and oropharyngeal cancers (OPSCCs)." (PMID 34452353, 2021). "Of the many signaling pathways related to tumor growth, the phosphoinositide 3-kinase (PI3K)/Akt/mTOR signaling pathway is frequently activated in cervical cancer and HPV-related head and neck squamous cell carcinoma (HNSCC)." (PMID 33482765, 2021). "Moreover, since the PI3K/AKT/mTOR pathway is considered to be a promising target for anticancer therapy, we discuss clinical implications for the treatment of HPV-positive cervical and head and neck squamous cell carcinomas." (PMID 31058807, 2019).
head and neck squamous cell carcinoma (continued). "This study tested the anti-head and neck squamous cell carcinoma (HNSCC) cell activity by GSK1059615, a novel PI3K and mTOR dual inhibitor." (PMID 28881606, 2017). "The key deregulated signaling pathways in head and neck squamous cell carcinoma (HNSCC) include EGFR, Ras, TGFβ, NFκB, Stat, Wnt/β-catenin and PI3-K/AKT/mTOR." (PMID 19284526, 2009). "Moreover, allosteric mTOR inhibitors can modestly reduce phosphorylated 4E-BP1 levels by inhibiting its phosphorylation and, as a result, are unable to effectively inhibit eIF4E-mediated cap-dependent translation initiation in human cancers, including head and neck squamous-cell carcinomas." (PMID 40563640, 2025). "Genomic analyses of head and neck squamous cell carcinoma (HNSCC) have highlighted alterations in the phosphatidylinositol 3-kinase (PI3K) signaling pathway, presenting a therapeutic target for multiple ongoing clinical trials with PI3K or PI3K/MTOR inhibitors." (PMID 32825725, 2020).
Hypertension (83 papers, 2011 to 2025). The presence of chronic increased pressure in the systemic arterial system. "The most common etiologies and risk factors are recurrent FSGS, rejection, mTOR‐inhibitors and hypertension." (PMID 41286586, 2025). "Considering IUGR is a risk factor for developing adulthood hypertension, it is very likely that amino acid sensing and mTOR are involved in the mechanisms behind programmed hypertension, although how this integration occurs awaits clarification." (PMID 36984857, 2023). "In a combined high-fructose and high-salt diet model, the beneficial actions by which maternal melatonin therapy protects adult rat offspring against hypertension were associated with increased renal protein level of mTOR." (PMID 36984857, 2023). "mTOR inhibitors have been associated with a lower risk of hypertension compared to calcineurin inhibitors when used in solid organ transplant recipients." (PMID 36211586, 2022). "Our findings extend prior work and suggest a possibility that the regulation of the mTOR signaling pathway is involved in developing OSA-associated hypertension through its interaction with the disturbance of the gut microbiome and sleep architecture." (PMID 34888100, 2021). "Taken together, our findings suggest that maternal melatonin therapy reprograms HF/HS-induced renal programming, and that programmed hypertension is associated with mediation of several nutrient-sensing signals and activating mTOR signaling and Nrf2." (PMID 29641494, 2018). "More importantly, mTOR inhibitors (sirolimus, everolimus) are also widely used as immunosuppressive agents to prevent organ rejection after organ transplantation, but they can also cause many side effects, such as hypertension, infection, and hyperlipidemia." (PMID 37190563, 2023). "We hypothesized that the changes in the gut microbiota and mTOR signaling pathway in patients with OSA are involved in developing OSA-associated hypertension." (PMID 34888100, 2021). "Therefore, our findings comprehensively suggest that the regulation of the mTOR signaling pathway is involved in developing OSA-associated hypertension through its interaction with the disturbance of the gut microbiome and sleep architecture." (PMID 34888100, 2021). "Disruptions in the sleep architecture and changes in the gut microbiota may interact in OSA-associated hypertension's physiopathology, and the mTOR signaling pathway may also be involved in this critical mechanism." (PMID 34888100, 2021). "Other anticancer therapies linked to hypertension include cisplatin derivatives, proteasome inhibitors, corticosteroids, alkylating agents, interferon-alpha, radiation therapy, inhibitors of the mammalian target of rapamycin (mTOR inhibitors), taxanes, vinca rosea alkaloids, and gemcitabine." (PMID 34712609, 2021). "Several drugs such as cisplatin derivatives, mTOR inhibitors, anthracyclines, alkylating agents may cause hypertension." (PMID 29755695, 2018). "Another future strategy may be the development of tools with high specificity and sensitivity for the risk prediction of severe hypertension to treatment with multikinase and mTOR inhibitors in RCC patients." (PMID 28796163, 2017). "It is usually mild and predominantly of tubular origin and is caused mainly by rejection, mTOR inhibitors, or hypertension; however, proteinuria could also be in the nephrotic range and of glomerular origin if caused by the recurrence of idiopathic FSGS or rejection." (PMID 41286586, 2025). "Therefore, this study investigated whether the OSA-associated hypertension mechanism is regulated by the gut microbiota and mTOR signaling pathway." (PMID 34888100, 2021). "The etiology of proteinuria should be identified (recurrence, rejection, mTOR‐inhibitors, hypertension, etc.)." (PMID 41286586, 2025).